CD4 (CD4 molecule)
Diseases named in the same sentence as CD4 in open-access papers (continued):
Sharing a sentence is not in itself a finding about the gene and the disease.
tumor (continued). "There is also evidence to show that tumor-specific CD4+ T cells are directly involved in orchestrating tumor relapse and escape in-vivo." (PMID 36005179, 2022). "TME analysis showed strong dependence of CD4 activation to reduce tumor burden and that the vaccine responders showed a high frequency of CD8 T-cell activation." (PMID 35651802, 2022). "The proportions of immune cell types, including B cells, CD8+ T cells, CD4+ T cells, macrophages, neutrophils, and dendritic cells, in tumor samples were calculated by TIMER." (PMID 35127943, 2022). "M1 macrophages and CD4+ T cells were also detected by immunohistochemistry between tumor and normal tissues." (PMID 36699449, 2022). "To study tumor-specific CD4+ T-cell dysfunction, we measured the expression of exhaustion markers, as well as IFN-γ, TNF-α, and IL-2 production of recovered SMARTA cells." (PMID 35784297, 2022). "METTL1 knockout mice have an anti-tumor microenvironment, with higher infiltration of CD4 + memory T cells, CD4 + naïve T cells, and CD8 + naïve T cells, and lower infiltration of Tregs and Th17 cells." (PMID 35590385, 2022). "Exposure to TCR hybridomas generated from tumor-infiltrating CD4+ T cells identified several reporter clones that carried a new tumor-specific antigen." (PMID 36700227, 2022). "Based on the time-dependent study results, nsECT treatment upregulated PD 1 expression on splenic CD4+ Tr1 cells, increased the expansion of splenic CD8+ T, CD4+CD8+ T, plasma cells and the proportion of tumour-associated pro inflammatory macrophages." (PMID 36551739, 2022). "It has been demonstrated that Th17 and Th1 CD4+T-helper cell subsets secrete anti-tumour inflammatory cytotoxic cytokines such as IL-17, IFNg, TNFa, and granzyme." (PMID 35743927, 2022). "The monocyte-derived inflammatory DCs (inf-DCs) contribute to anti-tumour activity by activating CD4+ and CD8+ T cells." (PMID 35406451, 2022). "The T-cell depletion suggests that CD8+ and CD4+ cells play a complicated, and sometimes counterproductive, role in the anti-tumor response for different tumor models." (PMID 35955613, 2022). "For example, CD4 Th2 cells are required for long-term memory responses, while Th17 cells can induce potent inflammation that can amplify anti-tumor immunity." (PMID 36362027, 2022). "CD4+ T cells constitute key players in anti-viral and anti-tumor immunity, as they produce cytokines and interact with other immune cells to activate CD8+ T cells and B cells." (PMID 36544761, 2022). "Similar to CD8+ tumor-infiltrating lymphocytes, CD4+ conventional T cells exhibited increased %PD-1 expression after HIPEC, with similar response associations for exceptional and poor responders." (PMID 35357903, 2022). "Experiments have confirmed that the tumor size in the typhus‐infected mice regresses related to the downregulation of CD44high and CD4 + CD25 + Treg cells." (PMID 35522104, 2022). "In a mouse model of breast cancer, docetaxel not only inhibited tumor growth but also upregulated CD4+ and CD8+ T cells proportion via IFN production." (PMID 35836810, 2022). "FAP-IL2v treatment did not alter the number of CD4+ T cells in tumors compared with the vehicle-treated group, but there was higher increase of CD4+ T cells in the tumor on day 7 compared to Day 5, which is consistent with the findings of the tracer." (PMID 35874707, 2022). "For example, in vivo models, lapatinib stimulates tumor infiltration by CD4 + CD8 + IFN-γ-producing T cells via a STAT1-dependent pathway." (PMID 35884366, 2022). "Tumor progression in both males and females was associated with the hepatic inflammatory patterns CD8+ >CD4+, Th1 > Th17 > Th2, NKT > NK, and M1 > M2." (PMID 35235789, 2022). "On the other hand, Tag7 can be exposed on the membrane of CD4 + cells and recognize Hsp70 in tumor cells." (PMID 35628562, 2022).
tumor (continued). "Previous studies demonstrated that TME contexture, including tumor-infiltrating CD4+/CD8+ T cells, macrophage M1, natural killer cells, and inflammatory cytokines, played vital roles in tumor progression and immunotherapeutic efficacy." (PMID 36006412, 2022). "A low concentration of glucose (0.1 mM) causes less production of phosphoenolpyruvate/PEP, a glycolytic metabolite that plays an important role in activating TCR-dependent Ca2+-NFAT signaling in anti-tumor CD4+ cells." (PMID 36319992, 2022). "We observed similar correlations of the expression level of STAT1 and IFIT3 with activated dendritic cells, activated NK cells, CD8 T cells and memory activated CD4 T cells, which were representative cells for anti-tumor immunity estimated by the CIBERSORT." (PMID 36311733, 2022). "In this study, we observed that the clonally expanded malignant tumor cells in ATLL are CD4 T-cells through scRNA-seq combined with TCR clonal analysis." (PMID 35464471, 2022). "HRS cells immune escape is facilitated by the protective shield conferred by CD4+ cells rosetting around tumor cells and by polarization towards Tregs." (PMID 35267668, 2022). "Data showed so far that for CD4-mediated tumor rejection is necessary antigen presentation by the TAMs and IFNγ signaling." (PMID 35903540, 2022). "The activation of mDC via TLR-8 by RSQ can effectively promote CD8+ T cell tumor recognition and polarize CD4+ T cells towards Th1 immune responses." (PMID 36297510, 2022). "Overall, our findings suggest a novel mechanism of CD4+ T cells in curtailing tumor metastasis and confirm their therapeutic role in combination with PD-L1 blockade in cancer immunotherapy." (PMID 35784297, 2022). "LAG-3 was found to negatively regulate the mitochondrial activity in naive CD4+ T cells, restricting the normal metabolism and expansion of naive CD4+ T cells and leading to T cell exhaustion and anti-tumor response." (PMID 35958563, 2022). "Opposing roles in cancer, either tumor-suppressive or tumor-promoting, have been found for immune cell types, such as CD4+ T-cells, CD8+ T-cells, natural killer (NK) cells, and macrophages." (PMID 35086565, 2022). "In the study, we found T cell CD4 memory activated, monocytes, macrophages M0, macrophages M1, and macrophages M2 were highly infiltrated in tumor samples." (PMID 35422890, 2022). "While it is hard to find differences between the CD4/CD8+ T cells infiltration in tumor or para-tumor tissues." (PMID 36612165, 2022). "Depletion of CD8+ T cells impaired but did not entirely ablate control of primary tumor growth and overall survival in the NBTXR3 + XRT + PLT group; like with CD4+ depletion, however, secondary tumor growth was completely unrestrained." (PMID 36123677, 2022). "A significant difference was found in CD3+ (stroma—p = 0.003, tumor—p < 0.001), CD8+ (tumor—p < 0.001), CD4+ (stroma—p = 0.013, tumor—p = 0.004), and CD45R0+ (tumor—p < 0.001) T cells." (PMID 35455743, 2022). "Accumulating evidence indicates that in addition to CD8+ T cells with direct cytolytic activity, CD4+ T cells play an orchestrated role in modulation of tumor immunology and immunotherapy." (PMID 35504878, 2022). "We next implanted 0.5 × 106 Panc47 FAK-wt and FAK−/− cells into the pancreas of C57BL/6 mice, culled mice 2 weeks post-implantation, and processed tumours for flow cytometry analysis to identify IL4+ CD4+ T-cells." (PMID 36138073, 2022). "Considering the role of adaptive immunity in anti-tumor responses, and T cells playing a crucial role in adaptive immunity against cancer, we further analyzed the proportion of CD4+ and CD8+ T cells in peripheral blood after the treatments." (PMID 35203498, 2022). "Preclinical models showing successful tumour rejection after the transfer of a small number of CD4 T cells into preconditioned tumour-bearing animals provided initial evidence for the clinical potential of CD4 CTL-based adoptive cell transfer (ACT) therapy." (PMID 35572552, 2022).
tumor (continued). "Tregs can release TGF-β, IL-10, and IL-35 during tumour immune escape, which decreases antitumour immunity, and suppresses antigen presentation by DCs and CD4+ Th cell activity." (PMID 36140243, 2022). "Given the dependence on CD8 T cells for tumor control, our data overall suggest that neoantigen vaccination induces specific CD4 T cells, and expands, and broadens the tumor-directed T cell response including neoantigen-specific CD8 T cells." (PMID 36569934, 2022). "CD4+ T cells can target tumor cells in various ways, either directly by eliminating tumor cells through cytolytic mechanisms (perforin/granzyme B-dependent manner) or indirectly by modulating the TME." (PMID 35205742, 2022). "It is well-established the activation of AhR in immune cells hinders efficient antitumor immunity via stimulation of antigen-presenting DCs, tumor-associated macrophages (TAMs), immunosuppressive Tregs and modulation of effector CD8 and CD4 T-cell functions." (PMID 35173722, 2022). "Although the increased perforin in CD4+ T cells was unexpected, recent work has shown the importance of anti-tumor responses by cytolytic CD4+ T cells." (PMID 35884414, 2022). "Densities of CD8+ and CD4+ T cell in tumor are identified as predictive biomarkers for combination therapy of PD‐L1 inhibition and nab‐paclitaxel." (PMID 34970866, 2022). "The opposing frequencies of CD4+ vs. CD8+ RepTILs between the two CRC patients, from which we succeeded in establishing PDX models, also provided the opportunity to associate tumor control with the specific ratio of TIL subsets." (PMID 35740548, 2022). "For example, TEXs from CD40L-gene modified 3LL lung tumor cells have the potent ability to activate DCs, resulting in significantly increased tumor antigen-specific CD4+ T cell proliferation and CD8+ T cell responses, revealing a powerful antitumor effect." (PMID 35582534, 2022). "FAL-ICG-HAuNS inhibited tumor growth and prolonged survival time of CT-26 tumor–bearing mice and B16 tumor–bearing mice, which was reversed by depleting either CD4+ or CD8+ T cells, demonstrating the important role of ICD in tumor killing." (PMID 35903337, 2022). "Concerning the profile of tumor-infiltrating cells, despite CD4-positive cells being found in a similar proportion in both groups, CD8-positive cells were significantly reduced in the exposed group." (PMID 36358618, 2022). "To examine the effect of CD4+ T cells on CD4-CIKs in tumor environment, we made a model for co-culturing CIKs and tumor cells (A549 or H520) in vitro based on a previous study." (PMID 35523765, 2022). "We observed that the majority of the ER+ high miR-18a-expressing samples expressed MMP9, and these tumor specimens also expressed a higher CD4/CD8 and a higher CD206/CD68." (PMID 35626709, 2022). "In contrast to CD8+ TILs, tumor-infiltrating CD4 regulatory T (Treg) cells with upregulated CD36 expression persisted in the TME and suppressed the antitumor immunity." (PMID 36275711, 2022). "Previous reports have shown that CD4+ T cells are essential for the optimal induction of anti-tumor responses by CD8+ T cell adoptive transfer and are involved in regulating PD-1 expression." (PMID 36611881, 2022). "Mature DCs present tumor associated antigens on MHC class I and MHC class II molecules to CD8+ T cells (CTLs) and CD4+ T cells (Th cells) with immature or memory phenotypes." (PMID 35418151, 2022). "The engagement of CD80 and CD40 on B cells replaces the need for CD4+ T cells to activate CD8+ cytotoxic T cells in anti-tumor responses." (PMID 35634306, 2022). "The TIGIT-Fc treatment enhanced effector NK cell functions and activated an anti-tumor T cell immune response via CD4+ T cells preventing their exhaustion." (PMID 35656508, 2022). "When mice received FMT from donor responders, they exhibited decreased tumour size, increased accumulation of CD4+CXCR3+ tumour infiltrating lymphocytes (TILs), and increased expression of PD-L1 on splenic CD4+ cells." (PMID 35565229, 2022).
tumor (continued). "Decreased tumor growth, pointing to an essential role for CD4+ and CD8+ T cells in the inulin-promoted antitumor phenotype." (PMID 36211513, 2022). "TIMER analysis indicated that RIMKLB transcription was closely related with several TIICs, including CD4+ and CD8+ T cells, B cells, tumor-associated macrophages (TAMs), monocytes, neutrophils, natural killer cells, dendritic cells, and subsets of T cells." (PMID 35444692, 2022). "Both CD4+ Tconv cells and Tregs from the tumor expressed less IL-2 than corresponding circulating T cells in the PR cohort." (PMID 36509285, 2022). "Our findings further highlight the importance of immunopeptidome-guided tumor antigen discovery in general, and underscore the central role of CD4+ T-cell responses for anti-cancer immunity." (PMID 35565389, 2022). "Altogether, this proteomic analysis showed that in presence of tumor specific CD4 T cells, the TAMs functionally switched from a tumor nurturing to a tumor-inflaming activity." (PMID 35903540, 2022). "A deeper characterization of these population in various human cancers have shown the involvement of SLAM family member 7 (SLAMF7) gene expression as a direct regulator of tumor-specific CD4+ T cell cytotoxicity." (PMID 35008422, 2022). "In vivo studies showed that Siglec-15 RNAi inhibited tumor growth and increased the CD4+/CD8+ ratio; however, this was offset by the overexpression of STAT1 and STAT3." (PMID 35769818, 2022). "The contribution of CD4 T-cell effector responses to the antitumor immune effects induced by STING ligand administration in the tumor environment was elusive." (PMID 35091453, 2022). "T cells are the main effector cells involved in anti-tumor immunity, and several studies have shown enrichment of CD4+ and CD8+ T cells in CLL." (PMID 36211334, 2022). "In our cohort, a considerable association was found between COPB2 expression and indicators of tumor immune microenvironment (TIME), such as histocompatibility complex class (MHC) I, and MHC II, CD4+/ CD8+ tumor-infiltrating lymphocytes." (PMID 35454945, 2022). "IL-10 inhibits the anti-tumor immune reaction, suppressing cytotoxic T cell functions by immune-suppressive (CD4+CD25+) Treg cells." (PMID 35955576, 2022). "With the aid of CpG, TAAs produced by PDT-induced tumor cell damage can enhance the presentation ability of DCs, which promotes the maturation of CD4+T cells and CD8+ T cells and the release of cytokines (including INF-γ, TNF-α)." (PMID 35832074, 2022). "These macrophages also inhibit the proliferation of CD8+ and CD4+ T cells in vitro and enhance tumor growth, mainly through PD-L1 in vivo." (PMID 36233088, 2022). "CD4+ Tregs are a highly immuno‐suppressive subset of CD4+ T cells, characterized by the expression of the master regulatory transcription factor FoxP3, and promote tumour progression by suppressing effective antitumor immunity." (PMID 35445563, 2022). "It has been found that in tumor immunity, CD4+ T cells can activate CD8+ T cells through a variety of mechanisms, allowing them to differentiate into CTL while maintaining and enhancing the anti-tumor response of CTL." (PMID 35402261, 2022). "The tumor infiltrating CD4+ and CD8+ T cells also had a mature immunophenotype, as they were more often CD57 positive and CD27 negative, as well as expressing the chemokine receptor, CXCR4." (PMID 35003893, 2022). "In this study, we further investigated the characteristics of CD4+ T cells after cryo-thermal therapy and determined their role in antitumor immune memory by tumor rechallenge and T-cell depletion." (PMID 35874660, 2022). "Here, we found that cluster A with the best prognosis was characterized by the highest CD4+T cell infiltration and exhibited an active immune phenotype, which was routinely so-called hot tumor." (PMID 35355983, 2022). "The deletion of c-MYC at the CD4+CD8+ stage of T cell development prevents tumour formation induced by NOTCH1." (PMID 35681778, 2022).
tumor (continued). "Similar percentages of CD8+ Tc were found in peripheral blood and biopsies, leading to an increase in the CD8/CD4 ratio at the tumor site." (PMID 36153593, 2022). "The abundance of tumor-infiltrating cDC2s can be an indicator for protective CD4+ T cell quality and better ICB response." (PMID 36353633, 2022). "In summary, these data suggest CD4+ Treg can use the perforin and/or granzyme pathway in vitro and in vivo, and have the potential to target DCs, B cells, T-cells, NK cells, and tumor cells to control immune responses." (PMID 35493508, 2022). "Beyond this function, we and others have shown that strictly tumor antigen-specific CD4+ T cells are capable of and required for anti-tumor responses when induced by vaccination." (PMID 36303101, 2022). "The TISIDB results showed that SELPLG was related to the abundance of CD4+ T cells in tumor-infiltrating lymphocytes, while SELPLG and its receptor SELL were also closely related to the cellular abundance of activated DCs24." (PMID 35710862, 2022). "Accumulating studies have found that tumor-infiltrating immune cells, including B cells, CD4+/CD8+ T cells, macrophages, neutrophils and dendritic cells, affect the efficacy of chemotherapy and immunotherapy and thus affect the prognosis of patients." (PMID 35309118, 2022). "This regimen showed for the first time evidence that objective tumour regression can be mediated by engineered MAGE-A3–specific CD4 T cells in a variety of cancer types." (PMID 35572552, 2022). "The transferred memory CD4+ T cells significantly protect the mice from lung metastasis relative to controls both on Day 11 and Day 15 after tumor inoculation." (PMID 35784297, 2022). "For instance, some novel T-cell-based vaccines are expected to perform the excellent tumor-killing function, by equipping polyclonal CD4+ T cells with antigen-specific exosomes." (PMID 35574366, 2022). "A lower CD4+/CD8+ ratio at the stromal internal tumor region indicated longer distant metastasis-free survival." (PMID 35454849, 2022). "Among them, plasma cells and activated CD4+T memory cells have important inhibitory effects on tumor growth." (PMID 35102149, 2022). "CD4+ T helper 2 (Th2) cells have been recently shown to possess the potential to efficiently eliminate early-stage tumor formation." (PMID 36467403, 2022). "In NSCLC patients, tumor-infiltrating B cells and CD4+ T cells inhabit in Tertiary lymphoid structures (TLS) and these are associated with better prognosis." (PMID 36620544, 2022). "A large proportion of M1 macrophages, M2 macrophages, CD8 T cells, and resting memory CD4 T cells were observed in the tumor group." (PMID 36360294, 2022). "STAT3 is mainly expressed in naive CD4+ T cells and activated p-STAT3 can modulate the transcriptional activity of target genes associated with tumor cell migration and invasion." (PMID 36437827, 2022). "Taken together, these data suggest that CD4+ T cells exhibit cytotoxic characteristics with functional activation, which can play a role in controlling tumour growth." (PMID 36376335, 2022). "PD-1 blockade increased tumor infiltration by both CD4 and CD8 T cells, reflecting the proliferation of non-Tregs due to reduced suppression from CD25- Tregs." (PMID 35449134, 2022). "Meanwhile, the IM@ZP group and the IM@ZP + NIR group were found to increase CD4 + T cells in tumor tissues than the PBS group." (PMID 35236356, 2022). "CD39 and/or CD73 (over)expression has been found on the surface of tumour cells, CAFs MDSCs, TAMs, Tregs and exhausted conventional CD4+ and CD8+ T cells." (PMID 36106115, 2022). "The tumor microenvironment in the low‐risk group was infiltrated with more memory B cells, CD8+ T cells, memory‐activated CD4+ T cells, follicular helper T cells, regulatory T cells, resting NK, M0 macrophages, M2 macrophages, and resting mast cells." (PMID 35293140, 2022).